CD4 (CD4 molecule)
Diseases named in the same sentence as CD4 in open-access papers (continued):
Sharing a sentence is not in itself a finding about the gene and the disease.
pancreatic adenocarcinoma (23 papers, 2006 to 2025). "In patients with pancreatic adenocarcinomas, infiltration of both CD4+ and CD8+ T cells is associated with better prognosis and significantly improved 5-year survival (28-, 30)." (PMID 36102418, 2022). "The few studies showing the response of those cells to pancreatic adenocarcinoma suggest that the immunity of CD4+ helper T cells in such neoplasm is directed toward a type Th2 suppressive immune response." (PMID 38954689, 2024). "That observation is reinforced by past results showing that both CD8+ and CD4+ T cells in pancreatic adenocarcinoma correlate better with the prognosis than when only one of them is detected in the environment." (PMID 38954689, 2024). "For example, in LUAD, higher Treg infiltration was seen in samples harboring oncogenic KRAS mutation (G12V/D), whereas the same mutation in pancreatic adenocarcinoma (PAAD) correlated with high infiltration of CD8+, CD4+ T cells, and Neutrophils." (PMID 30622534, 2018). "We have previously demonstrated a similar synergistic effect between tumour-infiltrating CD8+ T cells and CD4+ T cells in oesophageal squamous cell carcinoma and pancreatic adenocarcinoma." (PMID 16421594, 2006). "Importantly, GSDMD activation in intratumoral CD4+ T lymphocytes correlates with survival benefit and immunotherapy efficacy in colorectal cancer and pancreatic adenocarcinoma." (PMID 40759573, 2025). "This SNP is located in a DNAse hypersensitive site (DHS) for five cell types, including pancreas adenocarcinoma, B-lymphocyte (GM12891 and GM12892), medulloblastoma and CD4+ cells, and alters five regulatory motifs." (PMID 26835600, 2016). "We demonstrated that EGCG down-regulated IL-1R expression in CD4+ T cells, which was consistent with previous reports that EGCG reduced IL-1R expression in the pancreatic adenocarcinoma cells, although a different cell type." (PMID 24558360, 2014). "Meanwhile, in pancreatic adenocarcinoma, high SLC1A5 expression can reduce the infiltrating levels of CD8+ T cells, and is negatively correlated with the immune enrichment of CD8+ T cells, cytotoxic cells, NK cells and CD4+ T cells." (PMID 36902506, 2023). "We showed that, in coculture with human PBMCs, control RNF43-mutant HPAF-II pancreatic adenocarcinoma cells inhibit the stimulation of GMCSF and IFNγ production as well as CD4 and CD8 T-cell proliferation, effects that were reversed by preincubation of the HPAF-II cells with RXC004." (PMID 36922934, 2022).
pancreatitis (23 papers, 2010 to 2025). Inflammation of the pancreas. "In an experimental model, CD4+ T cell—depleted mice and nude mice (T cell—deficient) developed less severe pancreatitis than immunocompetent mice; after adaptive CD4+ lymphocytes transfer, this effect was partially reversed." (PMID 25938229, 2015). "Our study have shown Immunsuppression by HIV virus as measured by CD4 count < 200 is associated with increased number of admissions with pancreatitis and CD4 < 50 is further associated with a longer length of stay." (PMID 23390470, 2013). "Recent studies have shown that CD4+ T cell-related immune responses may be one of the causes of the development and progression of pancreatitis." (PMID 35745003, 2022). "Animal experimental studies have shown that Tα1 can alleviate pancreatitis by balancing CD3+/CD4+/CD8+ T cells and reducing cytokine release, reducing cell damage, thereby relieving the severity of the pancreas and improving the survival rate of SAP mice." (PMID 40599771, 2025). "In H&E staining of lung sections, a comparable pancreatitis-induced lung damage was seen in Cd4-cre Il6stfl/fl mice and wildtype littermates." (PMID 40560328, 2025). "In our study, we identified key hypoxia-related genes—RAP1GDS1, TOP2A, ADK, POLL, CD44, and CD4—in pancreatitis samples using methods such as WGCNA, XGBoost, and RF algorithms." (PMID 40787634, 2025). "Further investigations, including differential expression analysis and machine learning techniques, revealed six significant diagnostic markers for pancreatitis: RAP1GDS1, TOP2A, ADK, POLL, CD44, and CD4." (PMID 40787634, 2025). "In a mouse model of AP, pancreatitis induced hyperinflammation was accompanied by systemic immunosuppression, which is characterized by the induction of CD4+ T cells and in particular regulatory T cells." (PMID 40560328, 2025). "Thirty-four (53%) patients had a CD4 count less than 200 cells/mm3 at the time of their episode of pancreatitis." (PMID 23390470, 2013). "We aimed to address whether IL-6 or OSM have an impact on the significantly increased numbers of CD4+ T cells during the course of pancreatitis." (PMID 40560328, 2025). "We then conducted qRT-PCR on serum samples from five pancreatitis patients and five healthy controls to examine the expression levels of RAP1GDS1, TOP2A, ADK, POLL, CD44, and CD4." (PMID 40787634, 2025). "Exocrine injury presents with mixed CD4 and CD8 T-cell-mediated acinar and ductal damage of varying degrees or rarely as a sclerosing/mass-forming IgG4-related pancreatitis, thus with histologic overlap with type 1 AIP." (PMID 41209848, 2025). "A clinical trial including 12 patients with pancreatitis also showed that early HVHF performed over 3 days increased the number of peripheral blood monocytes, CD4+, CD8+ lymphocytes, and enhance monocyte HLA-DR expression." (PMID 38181043, 2024). "Compared to pancreatitis patients, CD3, CD4, and NK cells percentage were dramatically declined in PDAC patients (P = 0.0001)." (PMID 35034581, 2022). "A report of EUS-FNA for pembrolizumab-related pancreatitis also showed infiltration of T-lymphocytes, with a predominance of CD8+ cells over CD4+ cells." (PMID 35627900, 2022). "Wild type as well as mice lacking the GP130 receptor on CD4+ T cells showed a comparable systemic increase of IL-6 8 h after onset of pancreatitis." (PMID 40560328, 2025). "During the acute inflammatory phase of pancreatitis, activated Th1 cells stimulate other effector immune cells, such as B cells and CD8+ cytotoxic T lymphocytes, leading to pancreatic damage, which can be mitigated by depleting CD4+ T cells." (PMID 39940040, 2025). "According to the pathological findings of autopsy cases of ICI-related pancreatitis, along with the pathological findings of pembrolizumab necrotizing acute pancreatitis, significantly more CD8+ T cells than CD4+ T cells were detected in the remaining pancreatic parenchyma." (PMID 35627900, 2022).
pancreatitis (continued). "Consequently, CCR4−/− mice presented decreased IFN-γ-producing CD4+ and CD8+ T cells, an increased viral load and more severe pancreatitis." (PMID 31611578, 2019). "The concentration of IL-1ß does not increase during pancreatitis in the Cd4-cre Il6stfl/fl mice." (PMID 40560328, 2025). "By adoptive transfer of cells, we demonstrated that CCR4+ DCs are, at least in part, responsible for inducing CD4+ and CD8+ T cells-mediated IFN-γ production and for controlling the pancreatic injury, although CCR4− DCs may also play a role in the impairment of pancreatitis development." (PMID 31611578, 2019). "Galantamine significantly suppressed serum amylase levels and increased serum IL-10 levels in both WT and CD4+/ChATfl/fl mice receiving cerulein, indicating that ChAT expressing T-cells are not required for the protective effects of galantamine in pancreatitis." (PMID 37907853, 2023). "No cases of pancreatitis were recorded and the time since HIV diagnosis did not indicate any statistically significant differences in the means of the TG, serum amylase or CD4 count values." (PMID 30167336, 2018).
sporotrichosis (23 papers, 2012 to 2025). The commonest and least serious of the deep mycoses, characterized by nodular lesions of the cutaneous and subcutaneous tissues. "Contrary to this observation, monoclonal anti-Gp70 antibodies were capable of controlling experimental sporotrichosis caused by S. brasiliensis, and Gp70 peptides were found as good candidates to develop a CD4+-dependent protective immune response against subcutaneous sporotrichosis." (PMID 39866864, 2025). "Finally, there was one case of fixed cutaneous sporotrichosis caused by S. brasiliensis in a HIV infected patient with CD4>200 cells/μL." (PMID 25233227, 2014). "Case 8, a person living with HIV (PLHIV) with the fixed form of sporotrichosis, had a T CD4+ count of 309 cells/mm3 and a viral load of 4,512 copies/mL." (PMID 39705279, 2024). "IRIS is classified as the manifestation and/or worsening of pre-existing sporotrichosis by immune recovery, when the CD4+ T-cell count normalizes or HIV viral load decreases." (PMID 37108851, 2023). "There are also other immune cells involved in feline sporotrichosis, such as monocytes, CD4+, CD8low subset, and CD14+." (PMID 37233242, 2023). "Three patients were PLHIV, with a median CD4+ T lymphocyte count of 88 (range: 77–197) cells/μL and two of them are currently cured of sporotrichosis, while the woman was lost to follow-up." (PMID 37233246, 2023). "Peptides ZR8 and ZR3 demonstrated a better protective immune response mediated by CD4 + T cells and a good prognosis, being considered possible vaccine targets for the treatment of sporotrichosis." (PMID 37623561, 2023). "CD4+ T cells play a crucial role in the control of sporotrichosis, and these cells are exactly the main target of HIV infection." (PMID 34893422, 2022). "Cell-mediated immunity is also thought to play an important role in the control of feline sporotrichosis, since increased percentages of CD4 cells correlate with single lesions, well-organized inflammation, and lower fungal burden." (PMID 33652625, 2021). "Several recent studies have indicated that an imbalance of CD4+ T cell subsets and dysregulation of cytokines are closely correlated with host resistance to sporotrichosis." (PMID 34908455, 2021). "The CD4+ T cell count at the time of the diagnosis of sporotrichosis ranged from 1 to 348 cells/mm3, with 81% (17/21) bellow 200 cells/mm3, median of 46 cells/mm3 and viral load between undetectable and log 5.74." (PMID 33730026, 2021). "A fatal case of disseminated form of sporotrichosis was described in one patient with primary idiopathic CD4 lymphocytopenia." (PMID 30641918, 2019). "Although we did not observe any difference in the lesion fungal burden, the ZR8 and ZR3 immunized mice exhibited a protective immune response against sporotrichosis mediated by CD4+ T cells." (PMID 29520092, 2018). "The cell-mediated immunity during sporotrichosis involves interactions between CD4+ T cells, macrophages, dendritic cells, neutrophils and the release of soluble mediators which are protective and promote clearance of the infection." (PMID 28854184, 2017). "T CD4+ cells have a pivotal role for the control of sporotrichosis and these cells are exactly the main target of HIV infection." (PMID 25166475, 2014). "Both CD4+ T cells and macrophages are required in the granulomatous skin lesions of sporotrichosis; the presence of IFN-γ-producing CD4+ T cells is an essential component of host defense against this pathogen." (PMID 23226146, 2012). "We found that IL-18R was elevated in the lesional skin and S. globosa-infected CD4+T cells in this study, particularly within the Th2 subset; however, whether IL-9 sensitizes Th2 cells to IL-18 signals in sporotrichosis needs further investigation." (PMID 40489556, 2025).
sporotrichosis (continued). "In the most severe cases of feline sporotrichosis, co-infection with FIV or FLV has been reported, which is known to cause feline immunosuppression with low CD4+/CD8+ ratio and decreased levels of IL-4 and IL-12 and high levels of the anti-inflammatory interleukin IL-10." (PMID 37233242, 2023). "This study showed that HIV infection with a low CD4+ cell count aggravates sporotrichosis, since these patients had a more severe disseminated disease, 42-fold greater need for hospitalization, and 45-fold greater risk of death from this mycosis than individuals not infected with HIV." (PMID 34893422, 2022). "In addition, CD4+ T cells play a pivotal role in the control of sporotrichosis, and these cells are the main target of HIV infection." (PMID 35628791, 2022). "In addition, hospitalized patients had a mean CD4 T lymphocyte count of 125 cells/μL and deaths attributed to sporotrichosis occurred 45 times more." (PMID 30641918, 2019). "In humans, the decrease in CD4+ cell counts also correlated with disseminated sporotrichosis." (PMID 30500849, 2018). "Of these cell populations, CD4+ T cells and macrophages play an essential role for resolution of sporotrichosis, since athymic nude mice clearly demonstrate that loss of CD4+ T cells, but not CD8+ T cells, renders mammals susceptible to Sporothrix infection." (PMID 28854184, 2017). "Deeply immunocompromised individuals, especially those infected with the Human Immunodeficiency Virus (HIV) and T CD4 counts < 350 cells/ul lymphocytes, may present with the systemic form of sporotrichosis." (PMID 25949269, 2015). "Based on our previous clinical data our hypothesis is that patients co-infected by HIV with low CD4+ cell count are prone to worse outcomes as sporotrichosis evolves as an opportunistic condition." (PMID 25166475, 2014). "Sporotrichosis disease continues to occur in a more severe and widespread manner among HIV-positive subjects with lower CD4+ counts." (PMID 37108851, 2023). "With higher levels of IFN-β, IL-17A and IL-1β and increased numbers of CD4+ T cells in the lymph nodes and spleen, ZR8 peptide is the best vaccine candidate against subcutaneous sporotrichosis." (PMID 29520092, 2018). "In this study, all PLHIV had low CD4+ T cell counts and there was not a clear correlation between low CD4+ T cell counts and the outcome of sporotrichosis." (PMID 35628791, 2022). "The levels of IL-17 and IFN-γ are upregulated in acute disease and downregulated in nonacute disease, which means that CD4+ T cells participate in the body’s resistance to sporotrichosis." (PMID 34908455, 2021). "Nevertheless, the chronic course of the FIV disease that leads to the alteration of the CD4/CD8 ratio, could attempt against the clinical manifestation of severe sporotrichosis in cats with FIV." (PMID 33652625, 2021). "When considering retroviral infections, FIV-positive cats with sporotrichosis had significantly lower CD4+ and higher CD8+ cells than retrovirus-negative cats with sporotrichosis." (PMID 30500849, 2018). "Cats coinfected with these viruses show some differences in cytokine levels, showing higher levels of IL-10 and lower levels of IL-4, IL-12, and CD4+/CD8+, compared to other cats with sporotrichosis without coinfection with these viruses." (PMID 37233242, 2023).
thymic atrophy (23 papers, 2007 to 2025). "Old mice showed common signs of immune aging like thymic atrophy associated with decreased CD4+ effector T cell numbers." (PMID 34429153, 2021). "We found that LynΔN mice exhibited a severe thymic atrophy characterized by a massive depletion of the CD4+/CD8+ (DP) thymocyte sub-population, associated with an increase in CD19/B220 mature B cell in the spleen." (PMID 23071785, 2012). "Targeting accumulating reactive oxygen species with antioxidants has proven to be beneficial in protecting against age-related thymic atrophy, whereby treatment with the mitochondrial antioxidant SkQ1 reduced age-associated thymic atrophy and increased the number of CD4+ and CD8+ thymocytes." (PMID 32903477, 2020). "This includes thymic atrophy, the reduced plasticity of CD4+ T-cells, metabolic abnormalities, and various alternations in the proportions of T-cell subsets." (PMID 38727285, 2024). "Thymic atrophy resulted in significant loss of peripheral CD4+ and CD8+ T-cells with an increased frequency of CD4+Foxp3+ regulatory and activated/memory T cell subsets." (PMID 36814919, 2023). "Since our whole body inducible Clec16a mice displayed thymic atrophy, and T cells play a key role in regulating the immune responses, to specifically address the role of Clec16a in T cells we generated CD4-Cre Clec16aloxP mice." (PMID 30226884, 2018). "Using an A.C.-infected mouse model, we found that A.C.-infected mice developed severe thymic atrophy with dramatic impairments in thymocytes and TECs, particularly cortical TECs, which harbor CD4+CD8+ double-positive thymocytes." (PMID 28548945, 2017). "Such naïve cells, with their low natural rates of turnover and in the presence of thymic atrophy characteristic of adult humans, are difficult to replace and cumulative CD4 depletion results." (PMID 23637601, 2013). "Previous studies employing 24-h social defeat stress suggested that thymus atrophy is mediated by a decrease in the number of thymocytes, specifically the CD4+ and CD8+ subpopulation and, thus, reduces the functional capacity of T cells." (PMID 23300653, 2012). "The lethal infection with WR strain also induced severe thymus atrophy resulting in the reduction of CD4+CD8+ DP T cells in the thymus." (PMID 17326843, 2007). "Infection with Vaccinia virus (VV) induces severe thymic atrophy characterized by reduction of CD4+CD8+ DP thymocytes in the thymus, and gene A44L of VV is reported to be responsible for encoding 3β-hydroxysteroid dehydrogenase which can synthesize steroid hormones." (PMID 34113341, 2021). "Collectively, these data suggest that mannans extracted from the flo8 mutant could induce IL-10 production to inhibit C. albicans-induced thymus atrophy by blocking the apoptosis of immature CD4+ CD8+ T cells." (PMID 33154574, 2021). "Moreover, the circulating level of the proinflammatory cytokines IL-6 (associated with the decline in the efficacy of thymopoiesis) and TNF-α, which is shown to induce not only thymic atrophy, but also loss of CD28 expression on CD4+ T cells was investigated." (PMID 30086167, 2018). "This decrease in the T-PBL count in DA rats could reflect an enhanced migration of T cells, particularly CD4+ T cells into the CNS and/or immunization-induced thymic atrophy and impaired output of naïve T cells." (PMID 30086167, 2018). "We show here that LynΔN mice consistently exhibit thymic atrophy that correlates with both a net decrease in the CD4+/CD8+ Double Positive (DP) and an increase in Single Positive (SP) thymocyte sub-populations, but also display an increase of splenic mature B cell." (PMID 23071785, 2012). "Lethal infection with WR strain resulted in fewer lymphocytes and an altered phenotype of T cells in the lung compared to non-lethal infection and uninfected controls, and induced severe thymus atrophy with a marked reduction of CD4 and CD8 double positive (DP) T cells." (PMID 17326843, 2007).
thymic atrophy (continued). "Indeed, the constant stimulation of the immune system by HIV, associated with thymus atrophy with age, could be responsible for T-cell exhaustion and a reduced CD4/CD8 ratio, mainly driven by the loss of CD4+ and the expansion of CD8+ cells." (PMID 40303366, 2025). "Overall, in the context of infection-induced thymic atrophy, RU486 mediated inhibition of GC signalling was more effective at rescuing DN and CD4+ SP cells compared to ISP and DP cells." (PMID 28091621, 2017). "For example, upregulation of miR-181d leads to CD4+CD8+ T cell developmental disorder while also reducing the number of CD4+CD8+ T cells and increasing stress-induced thymic atrophy, but only a slight decrease in peripheral T cells was observed in mice after miR-181d transfection." (PMID 32581828, 2020). "This phenomenon occurred without any alterations in the frequency of CD4+CD8+ compartment, the major target cells in the T. cruzi induced thymic atrophy." (PMID 25330249, 2014).